INS (insulin)
Diseases named in the same sentence as INS in open-access papers (continued):
Sharing a sentence is not in itself a finding about the gene and the disease.
type 2 diabetes (continued). "In contrast, pharmacological activation of BCAA catabolism using sodium phenylbutyrate reduces plasma BCAA and glucose levels, improves peripheral insulin sensitivity, and enhances muscle mitochondrial oxidative capacity in individuals with Type 2 diabetes." (PMID 40289598, 2025). "Chronic infections exert longer-term effects through persistent low-grade inflammation that impairs β-cell function and insulin signaling—hallmarks of type 2 diabetes." (PMID 41404505, 2025). "The study answers an important research question about how the structure of the membrane affects the function of KATP and, in turn, insulin releases a common feature of metabolic syndrome and early stages of type 2 diabetes." (PMID 40137942, 2025). "This aligns with existing guidelines that recommend checking C-peptide to decide when to start insulin in type 2 diabetes patients." (PMID 41185830, 2025). "Pioglitazone is an insulin-sensitizing drug that ameliorates glycaemic control in type 2 diabetes, reduces triglycerides, and increases HDL levels, with low hypoglycaemic risk." (PMID 38778593, 2025). "For instance, an outpatient survey of type 2 diabetes patients in Sanming City, China, revealed that approximately 44.5% were undergoing insulin therapy." (PMID 40900896, 2025). "Those deficient in PDX1 expression have impaired beta-cell function and insulin production, which inevitably leads to type 1 and type 2 diabetes." (PMID 39858654, 2025). "By contrast, type 2 diabetes (T2D) is characterized by insulin resistance and defective insulin secretion by pancreatic beta cells." (PMID 39702741, 2025). "Compared to refined-grain diets, whole-grain diets reduced fasting insulin and enhanced glucose uptake, supporting breakfast’s protective role in preventing type 2 diabetes and cardiovascular diseases." (PMID 40869791, 2025). "Our results demonstrate that insulin’s ability to suppress plasma BCAAs is impaired in type 2 diabetes but is intact in individuals with obesity." (PMID 40404819, 2025). "We and others reported that common variants of type 2 diabetes, including some in MDG, predicted younger age of diagnosis of type 2 diabetes and earlier insulin requirement in both white European and Asian individuals after adjusting for clinical covariables." (PMID 39579208, 2025). "This intervention led to decreased levels of APOA-I, insulin, and blood glucose in individuals diagnosed with type 2 diabetes mellitus (T2DM)." (PMID 40573187, 2025). "As expected, patients with type 2 diabetes exhibited a several-fold higher daily average insulin level (3–5 times) than healthy individuals, consistent with the literature reports of hyperinsulinemia in this condition." (PMID 41465237, 2025). "Metformin, an insulin sensitizer widely used in type 2 diabetes, provides a useful pharmacological model in this regard." (PMID 41463298, 2025). "The relationship between vitamin D and the intestinal microbiota has emerged as a critical axis in the regulation of systemic inflammation and insulin sensitivity in type 2 diabetes." (PMID 40076782, 2025). "Most research on how olive oil affects type 2 diabetes and insulin sensitivity is brief and ignores the long-term, cumulative effects of olive oil use on metabolic health." (PMID 39940428, 2025). "Studies have shown that LEAP2 has an impact on insulin secretion, suggesting its potential involvement in glucose metabolism and possibly insulin sensitivity, which is crucial in managing conditions like type 2 diabetes." (PMID 39796232, 2025). "Type 2 diabetes mellitus (T2DM), now recognized as one of the most prevalent chronic metabolic diseases worldwide, is closely linked to insulin resistance, adipocyte dysfunction, and chronic low-grade inflammation." (PMID 41153793, 2025). "In the context of type 2 diabetes, insulin-stimulated glucose disposal of skeletal muscle is reduced by 50%, highlighting the importance of skeletal muscle in the pathogenesis of type 2 diabetes." (PMID 40441535, 2025).
type 2 diabetes (continued). "In accordance with these results, another study reported a 29% reduction in hospital admissions for hypoglycaemia for people with type 2 diabetes on prandial insulin after starting isCGM." (PMID 39460755, 2025). "In summary, we demonstrated that insulin’s ability to suppress circulating BCAAs is compromised in type 2 diabetes, whereas this response appears intact in obesity." (PMID 40404819, 2025). "Glucagon-like peptide-1 receptor agonists (GLP-1RAs), such as semaglutide and tirzepatide, have emerged as transformative agents for type 2 diabetes and obesity through their potent effects on weight reduction, insulin sensitivity, and cardiovascular outcomes." (PMID 41479489, 2025). "A powerful strategy for treating type 2 diabetes is combination therapy with basal insulin and semaglutide to harness their different mechanisms and target the various tissues involved in glucose regulation." (PMID 40937273, 2025). "When life expectancy is only days, insulin can be stopped in type 2 diabetes but continued with a further reduction in dose in type 1 diabetes." (PMID 40863223, 2025). "The most common form of diabetes is type 2 diabetes (T2D), characterized by inadequate insulin secretion and IR." (PMID 40573214, 2025). "Structured SMBG has also resulted in significant decreases in HbA1c among non-insulin-treated patients with type 2 diabetes." (PMID 41567897, 2025). "Improves glucose uptake, stimulates GLUT4 translocation, enhances insulin sensitivity, promotes adipocyte differentiation and lipid accumulation, increases adiponectin secretion, potentially beneficial for type 2 diabetes management." (PMID 39963239, 2025). "Irisin showed an inverse correlation with insulin-related metabolic pathways,suggesting its potential involvement in insulin resistance states such asobesity and type 2 diabetes." (PMID 40643080, 2025). "The study is also strengthened by the pragmatic inclusion criteria, which included patients living with both type 1 and type 2 diabetes requiring insulin." (PMID 40677318, 2025). "Here, we found that G3BP1, a stress granule marker downregulated in islets of subjects with type 2 diabetes, binds to insulin mRNA in glucose concentration-dependent manner." (PMID 40355555, 2025). "The disease arises from either reduced insulin secretion by pancreatic β-cells (type 1 diabetes) or impaired tissue responsiveness to insulin (type 2 diabetes [T2D])." (PMID 41142063, 2025). "This study compared the efficacy of intensive insulin therapy with empagliflozin (BBT + E) versus intensive insulin therapy alone (BBT) in hospitalised patients with type 2 diabetes admitted for hyperglycemia." (PMID 40828947, 2025). "Increased levels of ENaC subunits and NCC have also been observed in the mouse model of Type 1 diabetes induced by streptozotocin (STZ) and in Type 2 diabetes, partly attributed to increased insulin." (PMID 40617804, 2025). "Recent research implicates mitochondrial dynamics in regulating glucose metabolism and insulin signaling, contributing to the pathophysiology of obesity and type 2 diabetes." (PMID 41128021, 2025). "Persistent hyperglycemia and reduced insulin sensitivity eventually lead to β-cell exhaustion in the pancreas, driving the development of type 2 diabetes mellitus (T2DM)." (PMID 41169508, 2025). "Faecalibacterium prausnitzii, a species within this genus, has been suggested as a therapeutic option for type 2 diabetes due to its potential to enhance insulin sensitivity, improve lipid metabolism, and reduce inflammation." (PMID 40033386, 2025). "These cytokines can impair insulin signaling pathways, contributing to insulin resistance and the subsequent development of type 2 diabetes." (PMID 40658313, 2025). "Facility-level CGM uptake for patients with type 2 diabetes on insulin ranged from 4.2 to 59.3% (mean 30.7%, median 30.5%)." (PMID 40057678, 2025).
type 2 diabetes (continued). "Most importantly, bariatric surgery was found to achieve remission of type 2 diabetes in a lot of patients, largely due to improvements in insulin sensitivity and changes in gut hormones after the procedure." (PMID 41041606, 2025). "Crucially, GDM has long-term sequelae: women with GDM presented higher chances to develop type 2 diabetes postpartum, especially if they required insulin or had obesity." (PMID 40943638, 2025). "The inability of insulin to effectively inhibit hepatic glucose production has been identified as a key factor in the development of type 2 diabetes." (PMID 40286055, 2025). "Understanding the pathophysiological molecular mechanisms involved in insulin resistance and exhaustion of the pancreatic beta cells is essential for developing therapeutic strategies that can cure type 2 diabetes." (PMID 41009753, 2025). "Decreased insulin clearance in the setting of lower endogenous insulin secretion has also been described in youth and adults with obesity and prediabetes, and in type 2 diabetes." (PMID 39560746, 2025). "Type 2 Diabetes Mellitus (T2DM) is a chronic disease associated with insulin resistance and insufficient insulin secretion." (PMID 41487661, 2025). "Exercise training induces beneficial adaptations in skeletal muscle, including improved mitochondrial function and content, with intact responses in insulin-resistant individuals with obesity and in individuals with type 2 diabetes." (PMID 40404819, 2025). "Background/Objectives: Glucagon-like peptide-1 receptor agonists (GLP-1RAs), which were originally developed for managing type 2 diabetes by enhancing insulin secretion and reducing appetite, have emerged as promising candidates in alcohol use disorder (AUD)." (PMID 40722294, 2025). "The current study set out to disentangle the differential associations of somatic and cognitive-affective symptoms with insulin resistance and inflammation within a shared biological framework between depression and type 2 diabetes." (PMID 39951058, 2025). "Concretely, previous studies have observed that a low-carbohydrate bedtime snack in type 2 diabetes individuals resulted in an increased hepatic insulin sensitivity, a decreased hepatic glucose production overnight, and lower fasting glucose the next morning." (PMID 40573137, 2025). "Obese patients with autoimmune diabetes and preserved endogenous insulin secretion should be treated according to the guidelines for type 2 diabetes with regular assessment of endogenous insulin secretion, except for the use of sulfonylurea agents." (PMID 40226121, 2025). "The percentage of patients treated with insulin was higher in the hospital-based multidisciplinary group (71.6% vs. 32.2%; p < 0.001), even considering only patients with type 2 diabetes (58.8% vs. 31.0%; p = 0.004)." (PMID 39160371, 2025). "The decrease in pancreatic fat was accompanied by a reversal of type 2 diabetes, normalization of fasting glucose levels, and almost a return to baseline of the first phase insulin response of the pancreas after a glucose load." (PMID 41009753, 2025). "New oral antidiabetic medications, known as sodium–glucose co-transporter 2 inhibitors (SGLT2 I) can effectively treat type 2 diabetes mellitus (T2DM) by increasing renal glucose excretion through an insulin-independent mechanism." (PMID 40552161, 2025). "These indicators were risk of cardiovascular disease (blood lipids, blood pressure), type 2 diabetes (insulin, glucose), colorectal cancer (N-nitroso compounds), and osteoporosis (bone health; the ratio of markers for bone formation and resorption)." (PMID 39964546, 2025). "Given this gap, the present study aimed to investigate the relationships among pro/anti-inflammatory markers, mtDNA DAMPs, and insulin sensitivity/resistance in adults with type 2 diabetes." (PMID 41156500, 2025).
type 2 diabetes (continued). "Since glucose and insulin play an important role in adipocyte differentiation as well as in obese and type 2 diabetic patients, the effect of low glucose vs. high glucose concentrations on GDF15 protein quantity in cell supernatants was investigated by ELISA." (PMID 40820083, 2025). "For people with type 1 diabetes and many insulin-treated individuals with type 2 diabetes, CGM now directly informs treatment decisions, especially when integrated with automated insulin delivery (AID) systems." (PMID 40901276, 2025). "This combination of glucose intolerance, elevated blood glucose, and near-normal insulin levels differs from the typical type 2 diabetes phenotype." (PMID 40726918, 2025). "Another study that used a voice-based conversational AI interface, resembling the phone calls in the current intervention, found patients with type 2 diabetes logged daily insulin use and fasting blood glucose levels almost every day for about 4 months." (PMID 40829121, 2025). "In this retrospective analysis of two FCL studies in adults with type 1 diabetes and insulin-treated type 2 diabetes during unrestricted-living conditions, time spent in hypoglycemia and hyperglycemia was lower for those with type 2 diabetes." (PMID 38613227, 2025). "Metformin is commonly used to manage type 2 diabetes by reducing blood glucose levels through mechanisms such as reducing hepatic gluconeogenesis and enhancing insulin sensitivity." (PMID 40243881, 2025). "Type 2 diabetes mellitus (T2DM) is a chronic condition in which the body becomes resistant to insulin, disrupting normal metabolism and leading to persistent hyperglycemia." (PMID 41246137, 2025). "One study only included patients with type 2 diabetes, one study excluded all patients with type 2 diabetes on insulin and a further study excluded those on glucose‐lowering tablets." (PMID 39400428, 2025). "SGLT-2 inhibition increases circulating levels and expression of the zinc glycoprotein 2 gene in type 2 diabetes patients, improving insulin sensitivity." (PMID 40426925, 2025). "DNA methylation and other epigenetic modifications influence the insulin secretion and potassium channel regulation functions of the type 2 diabetes gene potassium voltage-gated channel subfamily J member 11 (KCNJ11), which is located on chromosome 11p15.1." (PMID 40225541, 2025). "Exercise not only improves insulin sensitivity and blood glucose levels in patients with type 2 diabetes but also reduces oxidative stress and lipid peroxidation." (PMID 40860658, 2025). "Thiazolidinediones (TZDs) are a significant class of second-line agents used to lower blood glucose by increasing insulin sensitivity in patients with type 2 diabetes." (PMID 40003982, 2025). "Particularly, adipose tissue ILC2s have been shown to promote metabolic homeostasis, adipose tissue “browning”, and systemic insulin sensitivity, protecting against obesity-induced metabolic disorders and type 2 diabetes." (PMID 40129978, 2025). "The results indicated that females in the DD group had a significantly higher intake of medications related to type 2 diabetes treatment and received insulin, and they had a significantly higher intake of pain medications, including analgesics (p < 0.05)." (PMID 40699752, 2025). "Previous studies have demonstrated that a carbohydrate-rich meal consumed as a bedtime snack can reduce morning hyperglycemia in non-insulin treated type 2 diabetes participants." (PMID 40573137, 2025). "It is estimated that the insulin-resistant state precedes the onset of type 2 diabetes mellitus (T2DM) by approximately 15 years." (PMID 39941639, 2025). "In the present study, we evaluated the role of insulin-mediated brain glucose metabolism in Type 2 diabetes by using two [18F]FDG-PET scans, at baseline (standard conditions) and after applying a HEC." (PMID 40510539, 2025).
type 2 diabetes (continued). "SARS Cov‐2 spike protein disrupts insulin signaling in type 2 diabetes as a target of the COVID‐19 vaccine in subject with type 2 diabetes (T2D), while metformin improved the insulin signaling variations induced by mRNA COVID‐19 vaccine boosters in mice." (PMID 41190280, 2025). "These epigenetic modifications directly influence genes related to insulin sensitivity and chronic inflammation, both key factors in the progression of type 2 diabetes." (PMID 40076782, 2025). "This was true both for healthy individuals and for patients with type 2 diabetes: a decrease in insulin level was accompanied by a reduction in triglyceride content, consistent with established views on insulin’s effect on lipogenesis." (PMID 41465237, 2025). "In type 2 diabetes, chronic hyperglycemia results from both pancreatic beta cells that are unresponsive to insulin secretion and insulin resistance in target tissues." (PMID 40487412, 2025). "In contrast to diabetic ketoacidosis, which reflects absolute or relative insulin deficiency and can occur in either type 1 or type 2 diabetes, patients with type 2 diabetes retain some insulin activity, preventing ketone production." (PMID 41035792, 2025). "It stimulates glucose-dependent insulin secretion, suppresses glucagon release, and delays gastric emptying, making it a cornerstone in managing type 2 diabetes and obesity." (PMID 40806100, 2025). "It is important to note that the negative regulatory effect of protein tyrosine phosphatase 1B (PTP1B) in the insulin signaling pathway makes it a promising therapeutic target for Type II diabetes mellitus treatment." (PMID 40284432, 2025). "Pro-inflammatory cytokines also impair insulin signaling, leading to hyperglycemia and type 2 diabetes." (PMID 41235339, 2025). "The insulin-regulated Glut4 is the most abundant transporter isoform in adipose tissue, and its expression is downregulated during obesity and type 2 diabetes." (PMID 40825507, 2025). "While GLP-1RAs and insulin act through different receptors, they share downstream signaling pathways, and by activating these overlapping pathways, GLP-1RAs can aid in restoring insulin signaling that is potentially impaired in patients with type 2 diabetes." (PMID 40630129, 2025). "Small fat cells in the subcutaneous fat tissue are insulin-sensitive and it is thought that an increased pool of small fat cells in the subcutaneous fat tissue protects from type 2 diabetes." (PMID 41009753, 2025). "Pancreatic β-cell dysfunction develops over time, affecting insulin production and resulting in chronic hyperglycemia, a defining feature of type 2 diabetes." (PMID 39940428, 2025). "Both in animal models and humans with type 2 diabetes, a significant decrease in insulin staining observed at the light microscope level was shown to be due to significant β-cell degranulation rather than β-cell death as seen at the electron microscope level." (PMID 39860066, 2025). "It is well-established for improving glucose metabolism, bolstering insulin sensitivity, and reducing major CVD risk factors such as hypertension and Type 2 Diabetes." (PMID 41421989, 2025). "Type 2 diabetes mellitus (T2DM) is a chronic metabolic disorder characterized by hyperglycemia resulting from inadequate insulin secretion or action." (PMID 41471293, 2025). "Type 2 diabetes (T2D), responsible for approximately 90–95% of all diabetes cases worldwide, arises from a combination of insulin resistance and impaired insulin secretion by pancreatic beta cells." (PMID 40282904, 2025). "Type 2 diabetes mellitus (T2D) is a chronic metabolic disorder characterized by insulin resistance and impaired insulin secretion, resulting in hyperglycemia." (PMID 40629349, 2025). "In mouse models of type 1 and type 2 diabetes, it ameliorated insulin-related defects and appeared to modulate the pro-inflammatory profile of insulin-reactive CD4+ T cells." (PMID 40724942, 2025).